TRPM2 (transient receptor potential cation channel subfamily M member 2)
Diseases named in the same sentence as TRPM2 in open-access papers (continued):
Sharing a sentence is not in itself a finding about the gene and the disease.
endothelial dysfunction (13 papers, 2012 to 2025). In vascular diseases, endothelial dysfunction is a systemic pathological state of the endothelium (the inner lining of blood vessels) and can be broadly defined as an imbalance between vasodilating and vasoconstricting substances produced by (or acting on) the endothelium. "Inhibition of TRPM2 channels may offer a therapeutic strategy for treating endothelial dysfunction associated with oxidative stress, as TRPM2-activated Ca2+ signaling is necessary for inducing endothelial insulin resistance in obesity." (PMID 39996055, 2025). "TRPM2 is a calcium ion-permeable cation channel that is activated in response to oxidative stress, whereby resulting in the increase in calcium influx in endothelial cells and further causing endothelial dysfunction." (PMID 36421426, 2022). "In addition, TRPM2 has been recently associated to diabetes-induced endothelial dysfunction." (PMID 34575985, 2021). "In contrast, FA-induced increases in TRPM4 expression and activation of TRPM2 channels, likely in response to FA-induced oxidative stress, were each shown to result in Ca2+ overload, an event that promotes cell death and endothelial dysfunction." (PMID 40996861, 2025). "In contrast to the previous studies on TRPM2-mediated endothelial dysfunction induced by oxidative stress, recent research has revealed that TRPM2 exerts vasodilatory effects upon activation by H2O2." (PMID 39007141, 2024). "Other major endothelial ion channels, including Piezo1 and select members of the transient receptor potential (TRP) family of channels (e.g. TRPM2/4) have each been shown to be modulated by saturated FAs in ways that could promote endothelial dysfunction." (PMID 40996861, 2025). "Ca2+ entry via TRPM2 may also initiate a process inducing endothelial dysfunction or apoptosis through actions on mitochondria." (PMID 33536876, 2020). "In light of the role of oxidative stress in the initiation and/or progression of vascular diseases, we believe that TRPM2 channels may represent a potential therapeutic target for the treatment of ROS-mediated endothelial dysfunction and vascular diseases." (PMID 22916222, 2012). "Beyond these limitations, it is important to consider that salt-induced endothelial dysfunction involves multiple interconnected pathways, including oxidative stress, ADMA accumulation, and activation of PARP, TRPM2, and inflammasome signaling." (PMID 41476791, 2025). "Furthermore, TRPM2-mediated extracellular Ca2+ entry could accelerate mitochondrial oxygen consumption and boost mitochondrial production of O2•−, which further exacerbates Aβ1-40-induced endothelial dysfunction." (PMID 34575985, 2021).
glioblastoma (13 papers, 2016 to 2025). The most malignant astrocytic tumor (WHO grade IV). "Selenium-mediated TRPM2 activation also enhanced ROS production and cell death in glioblastoma cells after treatment with docetaxel, an important antineoplastic agent used in the management of multiple metastatic and non-resectable tumor types." (PMID 37576339, 2023). "Resveratrol can also enhance the prooxidant and apoptotic effects of paclitaxel by activating the transient receptor potential cation channel, subfamily M, member 2 (TRPM2) channel in glioblastoma cells." (PMID 36307808, 2022). "Data suggest that TRPM2 channels function as ‘death channels’, because as a matter of fact, heterologous expression of TRPM2 in human embryonic kidney cells or A172 human glioblastoma cells facilitates oxidative stress-induced cell death." (PMID 32423430, 2020). "Accumulating evidences suggest that HYPX induced death and apoptosis is mainly through the increase of TRPM2 activation in the neurons such as DBTRG glioblastoma and hippocampus." (PMID 32296107, 2020). "The aim of this study was to evaluate the effect of combination therapy of RESV and PAX on activation of TRPM2 in DBTRG glioblastoma cells." (PMID 30984336, 2019). "Similarly, resveratrol has been reported to downregulate TRPM2 expression, disrupting oxidative stress–mediated survival pathways in glioblastoma cells." (PMID 40813985, 2025). "The combination of cisplatin and Eicosapentaenoic acid, a component of omega-3 polyunsaturated fatty acids recently shown to influence the effects of many anticancer drugs, also enhanced cisplatin-mediated oxidant effects and cell death through TRPM2 activation in glioblastoma cells." (PMID 37576339, 2023). "Similarly, honeybee venom melittin and silver nanoparticles enhanced cisplatin-mediated oxidant actions and cell death in glioblastoma cells through the activation of TRPM2." (PMID 37576339, 2023). "Similarly, we recently observed a modulator action of RSV on the TRPM2 channel activity in the DBTRG glioblastoma cells." (PMID 32296107, 2020). "In breast cancer and colorectal cancer, TRPM2 activates NRF2 signaling to enhance resistance to oxidative stress, while TRPA1 in glioblastoma alters mitochondrial dynamics and triggers apoptosis via increased fission, Ca2+ influx, and ROS production." (PMID 40813985, 2025). "And TRPM2 was downregulated in adrenocortical carcinoma (ACC), glioblastoma multiforme (GBM), and brain lower-grade glioma (LGG)." (PMID 37608401, 2023).
atherosclerosis (11 papers, 2022 to 2026). A disease characterized by the build-up of fatty material and calcium deposition in the arterial wall resulting in partial or complete occlusion of the arterial lumen. "More recently, with the use of TRPM2 knockout mice, we and others have demonstrated that TRPM2 promotes hypercholesterolemia-induced atherosclerosis via stimulating vascular inflammation." (PMID 40266108, 2025). "Taken together, our study, for the first time, showed that the E3 domain-based TRPM2 peptide P1 can be used in a vaccine platform to attenuate atherosclerotic progression in a mouse model of atherosclerosis." (PMID 40266108, 2025). "Yao, X., Cheung, W.T., Ying, F., Zhang, Y., Meng, Z. (2021): TRPM2-based peptide vaccine against atherosclerosis in ApoE knockout mouse model." (PMID 40266108, 2025). "Transient receptor potential channel isoform M2 (TRPM2) is an ROS-activated Ca2+-permeable ion channel that can promote atherosclerosis via stimulating vascular inflammation." (PMID 40266108, 2025). "Our current study lays the foundation for future clinical trials using TRPM2 peptide vaccine as a potential treatment for atherosclerosis." (PMID 40266108, 2025). "TRPM2 deletions protects against atherosclerosis by suppresses the activation of the CD36 signaling." (PMID 37588590, 2023). "We determined the effect of a TRPM2 antagonist ACA on atherosclerotic progression in an ApoE−/− mouse model of atherosclerosis." (PMID 35563730, 2022). "Our study provided concrete evidence that TRPM2 indeed contributes to the progression of hypercholesterolemia-induced atherosclerosis in an AAV-PCSK9 mouse model." (PMID 35563730, 2022). "The critical importance of TRPM2 in multiple processes of atherosclerosis prompted us to explore the possibility of using TRPM2 antagonists as anti-atherosclerotic agents." (PMID 35563730, 2022). "Transient receptor potential channel M2 (TRPM2) is a Ca2+-permeable cation channel activated by oxidative stress, which damages endothelial cell barrier function and further leads to ED or atherosclerosis in T2DM." (PMID 36421426, 2022). "In the present study, with the use of adeno-associated virus (AAV)-PCSK9 and TRPM2 knockout (TRPM2−/−) mice, we determined the role of TRPM2 in hypercholesterolemia-induced atherosclerosis." (PMID 35563730, 2022). "Our present study demonstrated a critical role of TRPM2 channels in promoting hypercholesterolemia-induced atherosclerosis in AAV-PCSK9 mouse." (PMID 35563730, 2022). "In the present study, with the use of AAV-PCSK9 and TRPM2−/− mice, we explored the possible role of TRPM2 in hypercholesterolemia-induced atherosclerosis." (PMID 35563730, 2022). "The results from theses analyses showed that knockout of TRPM2 markedly reduced the atherosclerotic lesion area in a mouse model of atherosclerosis." (PMID 35563730, 2022). "This study highlights the possibility of targeting TRPM2 and/or its signaling pathways as a potential therapeutic target for atherosclerosis." (PMID 35563730, 2022). "Taken together, the findings of our study demonstrated that TRPM2 contributes to the progression of hypercholesterolemia-induced atherosclerosis." (PMID 35563730, 2022). "A likely scenario is that excessive ROS activate TRPM2 to enhance the release of proinflammatory molecules from macrophages and vascular cells, consequently promoting atherosclerosis." (PMID 35563730, 2022). "Therefore, in this study, we chose to use TRPM2 peptides in a vaccine platform to activate anti-TRPM2 immune response as a means to protect against atherosclerosis." (PMID 40266108, 2025). "Therefore, our TRPM2 E3 region-based vaccine targets different steps/processes in atherosclerosis compared with most other vaccines that target LDL-antigens, providing an alternative therapeutic option." (PMID 40266108, 2025).
atherosclerosis (continued). "A recent in vivo study demonstrated that deleting Trpm2 or inhibiting TRPM2 activity in cultured macrophages suppressed the CD36 signaling cascade induced by oxidative low-density lipoprotein and TSP1, suggesting that TRPM2 is an effective therapeutic target for atherosclerosis." (PMID 39039680, 2024). "Inhibition of TRPM2 channel activity in macrophages decreases the production of ROS and pro-inflammatory cytokines, and reduces the size of atherosclerotic lesions in multiple mice models of atherosclerosis." (PMID 37588590, 2023). "TRPM2 enhances vascular reactivity during development of atherosclerosis." (PMID 37588590, 2023). "TRPM2 contributes to the progression of hypercholesterolemia-induced atherosclerosis." (PMID 37588590, 2023). "It was shown that both global and macrophage-specific TRPM2 deletions could protect Apoe-/- mice against atherosclerosis." (PMID 37588590, 2023). "In addition, a TRPM2 antagonist N-(p-amylcinnamoyl) anthranilic acid (ACA) was able to inhibit atherosclerotic development in an ApoE−/− mouse model of atherosclerosis." (PMID 35563730, 2022). "In the present study, we explored the possible role of TRPM2 in atherosclerosis." (PMID 35563730, 2022). "Therefore, TRPM2 is a key player in this vicious cycle of ROS overproduction and abnormal cytosolic Ca2+ rise in atherosclerosis progression." (PMID 35563730, 2022). "TRPM2 knockout can alleviate the development of aortic atherosclerotic plaque, and the related mechanism may be related to the reduction of the expression of various atherosclerosis-related proteins and the production of inflammatory cytokines and ROS by TRPM2 knockout." (PMID 38255767, 2024). "Mechanistically, they found that this effect was due to the reduction of oxLDL uptake and foam cell formation and that TRPM2 was an important regulator of the macrophage CD36 pathway, which is well known to be critical in the uptake of oxLDL in atherosclerosis." (PMID 38927523, 2024). "In accordance, inhibition of TRPM2 protected Apoe−/− mice from high-fat diet (HFD)-induced atherosclerosis by suppressing of CD36 signaling and the activation of macrophage pro-inflammatory activity, further consolidating the benefits of TRPM2 inhibition in mitigating severe inflammatory responses." (PMID 37576339, 2023). "However, despite such circumstantial evidence for a role of TRPM2 in atherosclerosis, until now there has been no concrete evidence demonstrating that TRPM2 indeed contributes to atherosclerosis in an animal model." (PMID 35563730, 2022). "However, the role of TRPM2 in atherosclerosis in animal models is not well studied." (PMID 35563730, 2022). "However, despite such circumstantial evidence implying that TRPM2 could play a role in atherosclerosis, the role of TRPM2 in atherosclerosis is still not well studied in animal models." (PMID 35563730, 2022).
epilepsy (10 papers, 2020 to 2025). A brain disorder characterized by episodes of abnormally increased neuronal discharge resulting in transient episodes of sensory or motor neurological dysfunction, or psychic dysfunction. "The hippocampus is a representative landmark structure for its physiological and diagnostic relevance in epilepsy; it is critical to definite the effect of Trpm2 deletion on hippocampal microglia after seizure." (PMID 40672432, 2025). "The neural hyperexcitability is one of main causes of epilepsy, and to confirm the role of microglial TRPM2 channel, we evaluated whether the deficiency of TRPM2 channel in microglia is essential to influence the excitability of hippocampal pyramidal neurons." (PMID 40672432, 2025). "Moreover, aberrant TRPM2 function seems to be associated with psychiatric and neurological diseases, such as stress-induced depression, epilepsy, ischemic brain injury, and glioma invasion." (PMID 32046066, 2020). "Our findings for the first time reveal microglial TRPM2 regulate the seizure development in an inflammation‐independent way and provide a new insight of epilepsy therapy." (PMID 40672432, 2025). "In intrahippocampal KA model, the seizure stage demonstrated that the development of epilepsy of Trpm2−/− mice was significantly faster than Trpm2+/+ mice." (PMID 40672432, 2025). "In rodent models of pilocarpine-induced epilepsy and cuprizone-induced multiple sclerosis, the deletion of TRPM2 reduced cytokine levels and attenuated inflammasome engagement within murine brain tissue." (PMID 39007141, 2024). "In PTZ-induced epileptic models, the knock-out of TRPM2 has shown efficacy in ameliorating epilepsy-induced hippocampal pathological damages, probably via the PARP1 downstream signaling pathway involving BNIP3." (PMID 40217519, 2024). "A knockout (KO) TRPM2 murine model showed reduced levels of neuroinflammation and neurodegeneration and increased epilepsy-induced psychological disorders, suggesting that TRPM2 favors the development and evolution of epilepsy-related brain injury." (PMID 36620667, 2022). "Traditionally, it is considered that epilepsy is mainly caused by hypersynchronous firing of neurons; however, our results revealed that neuronal TRPM2 channel is not involved in later stage of seizure development." (PMID 40672432, 2025). "Here, we unveil a novel mechanism though which microglial TRPM2 mediates epilepsy development." (PMID 40672432, 2025). "Moreover, the expression of TRPM2 is increased in the hippocampus after epilepsy occurred and Trpm2 knockout alleviated the level of neuroinflammation and glial cell activation and ameliorated the epileptic‐related psychological disorders." (PMID 41399206, 2025). "To investigate the role of TRPM2 channel in epilepsy, we first evaluated the seizure behaviors of Trpm2−/− mice in different mouse seizure models, including MES‐ and pentylenetetrazole (PTZ)‐induced seizure model, intrahippocampal KA model, and hippocampal kindling model." (PMID 40672432, 2025). "The neuroprotective effect of TRPM2 knockout could decrease neuronal apoptosis via PARP‐1/BNIP3/AIF in epilepsy." (PMID 38801174, 2024). "However, our study found that when tissues were collected immediately after GSs, the levels of inflammatory factors did not change, indicating that TRPM2 in microglia may contribute to epilepsy in a noninflammation‐dependent manner." (PMID 40672432, 2025).
acute myeloid leukemia (9 papers, 2020 to 2023). Acute myeloid leukemia (AML) is a group of neoplasms arising from precursor cells committed to the myeloid cell-line differentiation. "Recently, TRPM2 has been demonstrated to regulate the expression of CREB in an acute myeloid leukemia cell line." (PMID 38390373, 2023). "Our research suggests that there is a different regulation of PARP1, PARP2, PARP3, and TRPM2 gene expression in acute myelogenous leukemia cells." (PMID 32423430, 2020). "Our research suggests that there is a different regulation of PARP1, PARP2, PARP3, and TRPM2 genes expression in acute myelogenous leukemia cells." (PMID 32423430, 2020). "Here, we show that TRPM2 is highly expressed in acute myeloid leukemia (AML)." (PMID 32312983, 2020). "PARP1, PARP2, and TRPM2 genes at mRNA level deregulate in acute myeloid leukemia cells." (PMID 32423430, 2020). "Firstly, we discuss the compelling evidence coming from the analysis of TRPM2 in acute myeloid leukemia (AML)." (PMID 37507867, 2023). "TRPM2 is overexpressed in cells from patients with acute myeloid leukemia (AML) and in AML cell lines (e.g. Kasumi-1, U937, KG-1, MV-4-11, SKNO1, THP-1, MonoMac-6, AML-193, MOLM13 and SHSY5Y)." (PMID 36330491, 2022). "The results found that the bone marrow cells of the patients with acute myeloid leukemia (AML) show overexpression of PARP1 and PARP2 genes and decreased TRPM2 gene expression." (PMID 32423430, 2020). "In our studies we showed that in the bone marrow cells of patients with acute myeloid leukemia, PARP1 and PARP2 genes are overexpressed and TRPM2 gene is down-regulated, which may suggest disturbed signaling between these genes." (PMID 32423430, 2020). "In acute myelogenous leukemia cells, PARP1, PARP2, and TRPM2 gene mRNA levels deregulate." (PMID 32423430, 2020). "Interestingly, the bone marrow cells of patients with acute myelogenous leukemia show over expression of PARP1 and PARP2 genes and decreased TRPM2 gene expression." (PMID 32423430, 2020).
hepatocellular carcinoma (9 papers, 2015 to 2024). A malignant tumor that arises from hepatocytes. "TRPC1 and TRPM7 were reported to be expressed in H4-IIE rat liver hepatoma cell lines, while TRPM2 channels were recently linked to APAP-induced oxidative stress and Ca2+ overload in mouse hepatocytes." (PMID 26903865, 2016). "Recently, indirect CaM modulation of TRPM2 has been described in the field of hepatocellular carcinoma (HCC)." (PMID 37894842, 2023). "Given the important role played by ROS in the development of non-alcoholic fatty liver disease and hepatocellular carcinoma, it is very likely that liver cell TRPM2 channels, activated by ROS, are involved." (PMID 34439491, 2021). "Of particular interest is the role of TRPM2 in liver injury induced by paracetamol toxicity and ischemia–reperfusion, and in the progression of non-alcoholic fatty liver disease to fibrosis, cirrhosis, and hepatocellular carcinoma." (PMID 34439491, 2021). "Studies to date provide evidence that TRPM2-mediated Ca2+ entry contributes to drug-induced liver toxicity, ischemia–reperfusion injury, and the progression of non-alcoholic fatty liver disease to cirrhosis, fibrosis, and hepatocellular carcinoma." (PMID 34439491, 2021). "Among members of transient receptor potential (TRP) channels activated in response to oxidative stress, we here identify that redox-sensitive TRPV1, TRPC1, TRPM2, and TRPM7 channels underlie Ca2+ entry and downstream cellular damages induced by APAP in human hepatoma (HepG2) cells." (PMID 26903865, 2016). "There is suggestive evidence that TRPM2 channel activity may be altered in steatotic hepatocytes and hence may contribute to the progression of non-alcoholic fatty liver disease to cirrhosis and hepatocellular carcinoma." (PMID 34439491, 2021). "In conclusion, this is the first study to systematically and comparatively analyze the contributions of redox-sensitive TRP channels such as TRPV1, TRPC1, TRPM2, and TRPM7 to human hepatoma cell death induced by APAP overdose." (PMID 26903865, 2016).